ARG1 (arginase 1)
Diseases named in the same sentence as ARG1 in open-access papers (continued):
Sharing a sentence is not in itself a finding about the gene and the disease.
tumor (continued). "High levels of ARG1 expression by MDSCs can accelerate the depletion of L-arginine in the tumour microenvironment, which subsequently inhibits T-cell proliferation by causing low expression of T-cell receptors and thus suppression of the cell cycle in T cells." (PMID 24741628, 2014). "In fact, VSSP treatment not only prevented up-regulation of Arg1 and Nos2 on tumor-induced MDSCs but also reduced MDSCs-mediated down-regulation of CD3ζ chain on antigen-specific CD8+ T cells." (PMID 24829762, 2014). "Sildenafil, a phosphodiesterase-5 inhibitor, reduced arginase 1 and nitric oxide synthase-2 expression in a mouse tumor model." (PMID 24995313, 2014). "In several preclinical trials the use of COX2 inhibitors, such as celecoxib, down-regulated ARG1 expression, delayed tumor growth, and stimulated anti-tumor response." (PMID 24605112, 2014). "In murine models of breast and colon cancers, treatment with sidenafil decreased arg1 and iNOS expression, resulting in increased numbers of tumor-infiltrating CD8+ T-cells." (PMID 24202450, 2013). "Arginase-1 was chosen, because of its ability to diminish anti-tumour immunity by interfering with the activation of T-cells." (PMID 24204595, 2013). "The current study evaluated safety, pharmacokinetics (PK)/ pharmacodynamics (PD) parameters, and potential anti-tumor activity of pegylated recombinant human arginase 1 (peg-rhArg1) in advanced HCC patients." (PMID 22426640, 2013). "ARG1 can profoundly impair T cell function at the tumor site by L-arginine depletion, triggering the amino acid starvation response and apoptosis in lymphocytes." (PMID 22428007, 2012). "Another enzyme that has been implicated as an immunoregulatory molecule in myeloid cells including DCs in the tumor context is arginase-1 (ARG1)." (PMID 22969767, 2012). "Although the first experiments underlying the importance of L-arginine metabolism in cancer were performed more than 50 years ago, only recently has the role of Arg-1 in tumor growth and escape from the immune surveillance been clarified." (PMID 22481970, 2012). "The level of arg-1 mRNA was elevated in tumor-derived CD11b+ cells, thus we measured arginase activity in brain extracts." (PMID 21901144, 2011). "Similar to ARG2, inhibition of ARG1 expression led to decreased tumor cell proliferation, reduced l-arginine metabolism and reduction of their immunosuppressive potential." (PMID 20711410, 2010). "Interesting, "M2-like" tumor infiltrating myeloid-derived suppressor cells (MDSCs) is a cell population with a phenotype similar to M2 macrophages expressing high levels of arginase-1 and S100A9 protein." (PMID 20470445, 2010). "A significant, 1.8 fold increase in arginase 1 protein content in tumors of diclofenac treated mice was also measured by western blot analysis of tumor homogenates." (PMID 20856806, 2010). "Surprisingly, in contrast to other COX-2 inhibitors, diclofenac increased arginase activity/arginase 1 protein content in tumor stroma cells, peritoneal macrophages and white blood cells by 2.4, 4.8 and 2 fold, respectively." (PMID 20856806, 2010). "Furthermore, neutrophil‐derived immunosuppressive factors such as Arg1 and ROS inhibit NK cell anti‐tumour activity by depleting microenvironmental nutrients or inducing oxidative stress." (PMID 41491612, 2026). "Mechanistically, hypoxia acts through tumor-fibroblast crosstalk to increase IL-6 expression in fibroblasts; in turn, fibroblast-derived IL-6 induces expression of arginase 1 (ARG1), a key mediator of immunosuppression, in macrophages via activation of the JAK/STAT signaling pathway." (PMID 42041553, 2026). "These pathways may intersect with tumor metabolic reprogramming, as in the Warburg effect, which modulates macrophage ARG1 expression and suppresses T cell activation." (PMID 41490177, 2026).
tumor (continued). "It has been well recognized that M-MDSCs and PMN-MDSCs both express multiple immunosuppressive signals within the tumor microenvironment, including arginase-1 (ARG1), inducible nitric oxide synthase (iNOS), programmed death-ligand 1 (PD-L1), and interleukin 10 (IL-10)." (PMID 41614948, 2026). "Immunohistochemistry (IHC) staining showed that while the UCEs CPS1, ASS1, ASL, and ARG1 were highly expressed in the periportal (zone 1) and midzonal areas (zone 2) in healthy control mice, they were expressed at various levels in the end-stage tumor tissues." (PMID 41512056, 2026). "We discovered earlier unknown functions of the proteasome LMP2 subunit to facilitate the formation of tumor conglomerates and maintain Chil3 and Arg1 expression in immunosuppressive M2 macrophages." (PMID 40918453, 2025). "Arginase 1 (ARG1) has the ability to degrade arginine, which inhibits the anti-tumor response." (PMID 41019086, 2025). "Additionally, neutrophils can inhibit T-cell activity by secretion of reactive oxygen species and arginase-1, fostering an immunosuppressive environment that facilitates tumor progression." (PMID 40142281, 2025). "Moreover, anti-inflammatory factors, including TGF-β, IL-10, IL-13, and Arg1 in tumor tissues were notably downregulated by sh-TBX21 injection." (PMID 41573646, 2025). "TAMs can polarize into multiple subtypes, influenced by factors such as colony‐stimulating factor 1 (CSF‐1) and chemokine (C‐C motif) ligand 2 (CCL2), and often express M2‐like markers including CD206, CD163, Arginase 1 (ARG1), and IL‐10, all of which promote tumor progression." (PMID 40553053, 2025). "Different subsets of immunosuppressive TAMs (SPP1-C1Qa/b, proliferating, Nos2 glycolytic and OXPHOS TAMs) exhibited high expression of Trem2, Axl, Tim3 and Arg1, known markers of a pro-tumor phenotype, and were proportionally decreased in response to ACTM-838 treatment (except OXPHOS TAMs)." (PMID 41048107, 2025). "This lactic acid derived from tumor cells is a potent inducer of ARG1 expression in TAMs." (PMID 41281760, 2025). "In ST2-deficient mice, tumor-infiltrating CD11b+CD11c- macrophages, exhibit decreased expression of the co-stimulatory receptor CD86 and produce increased levels of the immunosuppressive enzyme Arg1." (PMID 39931535, 2025). "The ARG1 inhibitor CB-1158 has demonstrated the potential to convert immunosuppressive tumor microenvironments into proinflammatory states, thereby alleviating T cell suppression and reducing tumor growth." (PMID 40342932, 2025). "Moreover, we found that in the same brains, Arg1+ and iNOS+ microglia were significantly clustered at the site of tumor metastasis." (PMID 40444044, 2025). "In the present study, we found that after BM of BC cells, Arg1+ microglia were significantly aggregated at the site of tumor metastasis, and the levels of cytokine IL6, chemokine CCL2, were significantly increased, suggesting an immunosuppressive microenvironment following BC-BM." (PMID 40444044, 2025). "However, while recent evidence from tumor-bearing mice indicates that Arg1 knockout alone is insufficient to prevent cardiac atrophy, it is important to consider that heart function is not solely determined by cardiac mass." (PMID 40474277, 2025). "Through Arg1-mediated arginine depletion, dendritic cells may contribute to T cell exhaustion, a key factor in tumor immune evasion and immunotherapy resistance." (PMID 40438606, 2025). "Furthermore, 97% of HCCs showed albumin positivity in >50% of tumor cells, compared to only 76% for HepPar1 and 70% for Arg-1." (PMID 40941632, 2025). "Furthermore, tumor stem cells tend to co-express arginase-1 (ARG1) and iNOS, often depleting L-arginine by consuming it metabolically, which contributes to immunosuppression within the TME." (PMID 41036604, 2025).
tumor (continued). "Moreover, Arg1 expression in TAMs is sustained by a complex tumor milieu, including IL-4/IL-13, IL-10, TGF-β, lactic acid, hypoxia, and metabolic crosstalk, which is not fully recapitulated by IL-4 alone in vitro." (PMID 41465516, 2025). "Moreover, MDSCs have been shown to be a major source of ARG1 in the tumor setting, further supporting their immunosuppressive function." (PMID 41573553, 2025). "In addition, myeloid-derived suppressor cells exert immunosuppressive effects by producing arginase-1, inducible nitric oxide synthase, and other inhibitory substances, thereby playing an important role in reshaping the tumor immune microenvironment." (PMID 39759121, 2025). "Notably, NOS2 and ARG1 are expressed not only by tumor cells but also by immune cells that infiltrate the TME." (PMID 41573553, 2025). "Analysis of tumor immune profiles with flow cytometry showed that treatment with MRTX1133 decreased tumor infiltration of bone-marrow–derived monocytes (CD11b+Ly6ChiLy6G–) and, particularly macrophages (CD11b+F4/80+IA/IE+) and protumoral macrophages (ARG1+ macrophages)." (PMID 39883522, 2025). "Additionally, the MCSV promoter was replaced with the Arg1 promoter (pCDH-Arg1-Tri-TRAIL), enabling a targeted response to tumor-associated stimuli due to elevated Arg1 expression in RAW264.7 cells." (PMID 40110051, 2025). "In non-small cell lung cancer (NSCLC), tumour-derived ANXA2 activates Toll-like receptor 2 (TLR2) receptors and downstream signalling on tumour-associated neutrophils (TANs), subsequently promoting ARG1 expression." (PMID 40234383, 2025). "In addition, mDTX2i treatment on tumor cells inhibited neutrophil chemotaxis and ARG1 expression of neutrophils." (PMID 39733452, 2025). "Metabolomic studies have revealed that in the liver metastasis microenvironment, an imbalance in arginine metabolism (upregulated ARG1) inhibits M1 polarization and induces macrophages to produce polyamines via the urea cycle, thereby accelerating tumor cell invasion." (PMID 41164182, 2025). "Compared to IMs, recMacs were enriched for canonical tumor-promoting transcripts including Spp1, Vegfa, Arg1, and Cd274 Together, these data suggest that while both populations contribute to immune regulation, recMacs are more transcriptionally aligned with tumor-promoting programs." (PMID 40630529, 2025). "mRNA expression of CXCL9, iNOS, and IL-12β, anti-tumor macrophage markers, was elevated, while mRNA expression of IFNγ, TNFα, ARG-1, TGFβ, IL-10, and VEGFa, pro-tumor macrophage markers, was significantly lower in TAMs isolated from the prostates of RON∆Epi/TRAMP+ compared to RONF/F/TRAMP+ mice." (PMID 40282397, 2025). "Specifically, MDSCs produce abundant Arg-1 and iNOS, inducing oxidative stress while depleting essential amino acids (e.g., L-arginine, L-cysteine) to suppress T-cell function-ultimately enabling tumor immune escape and systemic immunodeficiency." (PMID 41286750, 2025). "In addition to Trp, Arg metabolism in DCs also promotes tumor growth, and ARG-1 in DCs can catabolize Arg to polyamine production." (PMID 40696413, 2025). "In this context, the tumor microenvironment naturally promotes mixed iNOS+/Arg1+ phenotypes, and TTFields appear to overlay an iNOS+, pro-inflammatory program onto an Arg1-maintaining background, generating more “hybrid” states rather than fully depleting M2-like TAMs." (PMID 41465516, 2025). "However, with LNP-CTNNB1 treatment, tumor cells begin to express Cyp2f2, Arg1, and Ass1 along with diminished expression of Cyp2e1, Cyp1a2, Oat and others." (PMID 40442146, 2025).
tumor (continued). "Furthermore, it alters the tumor immune landscape by targeting MDSCs through modulation of the Arginase 1 (Arg-1)/inducible nitric oxide synthase/STAT3 axis and related signaling pathways." (PMID 40869364, 2025). "Using a xenograft SCID mice model these authors also demonstrated that CCL-2/MCP-1 is responsible for the monocyte recruitment into the tumor whereas IL-13 polarize these cells into M2 subset characterized by high expression of arginase-1 and low expression of inducible nitric oxide synthase (iNOS)." (PMID 40868818, 2025). "Additionally, arginase 1 (ARG1) and TGF-β are potent immunosuppressive proteins commonly secreted by tumor-promoting cells such as M2 tumor-associated macrophages (TAMs) and subsequently inhibit CD8+ T-cell effector function." (PMID 40867322, 2025). "Thus, it is possible that PAI-1 inhibition alone did not change the amount of infiltrating immuno suppressive microglia and macrophages (CD206+) but did decrease Arg1 expression throughout the tumor." (PMID 40684232, 2025). "In tumor-associated macrophages (TAMs), OXPHOS and fatty acid oxidation dominate, mediating H3K4me3 modifications via PPARγ to promote anti-inflammatory genes (e.g., ARG1, MRC1) and drive tumor progression." (PMID 40959285, 2025). "Furthermore, this drug also diminished the expression of immunosuppressive genes such as Arg1, Ncf1, and Ncf4 in tumor-infiltrating PMN-MDSCs, especially when combined with the dual Phosphoinositide 3-Kinase (PI3K)/mTOR inhibitor dactolisib." (PMID 40227814, 2025). "We systematically evaluate conventional markers, such as hepatocyte paraffin 1 (HepPar1), arginase-1 (Arg-1), and glypican-3 (GPC3), as well as emerging biomarkers, detailing their diagnostic sensitivities and specificities in HCC with varied tumor differentiation." (PMID 40941632, 2025). "Furthermore, tumor microenvironment induces imDCs to secret suppressive factors like Il-10, Arg1, Ido1 and Ido2." (PMID 40730800, 2025). "It is believed that the infiltration of CD8+ T cells inhibits tumor development, while myeloid-derived suppressor cells and TAMs deplete extracellular Arg by producing a large amount of ARG1, thereby activating GCN2 and inhibiting the proliferation of CD8+ T cells." (PMID 41281760, 2025). "By secreting chemical substances such arginase-1 (Arg-1), inducible nitric oxide synthase (iNOS), and reactive oxygen species (ROS), MDSCs weaken anti-tumor immunity, especially T cell function, and make it easier for neoplastic cells to avoid immune surveillance." (PMID 40149640, 2025). "Surprisingly, there was a reduction in ARG1 gene expression in tumour samples (2.50-fold decrease, mean LFC = −1.32 ± 0.30; p = 0.0008, 95% CI = −2.06 to −0.58), correlating to decreased levels of immunosuppressive ‘M2’ tumour-associated microglia/macrophages (TAMs)." (PMID 41034696, 2025). "Similarly to IDO1-driven tryptophan depletion, ARG1-mediated arginine depletion impairs the metabolic fitness and differentiation of tumor infiltrating lymphocytes (TILs)." (PMID 40507361, 2025). "Additionally, they contribute to the depletion of arginine in the microenvironment by secreting reactive oxygen species and arginase 1 (ARG1), thereby creating a conducive environment for the colonization of circulating tumor cells." (PMID 41164182, 2025). "However, the complete inhibition of Notch signaling to reduce arginase-1 activity is likely to affect cellular processes unrelated to tumor development." (PMID 39702544, 2024). "Over time, the expression of these inflammatory genes was rapidly declined, while the expression of factors that promoted tumor growth (such as Vegfa and Arg1 that promoted tumor angiogenesis, and the signature genes Trem2 and Apoe that promoted tumor growth) continued to rise." (PMID 39867913, 2024). "Finally, when fixed tumor slices were immunostained for arginase-1 protein, tumors from Ddr2−/− hosts had decreased arginase-1 expression." (PMID 37996700, 2024).
tumor (continued). "The extracellular vesicles produced by this cell line can polarize neutrophils towards the pro-tumour (N2) subtype, which increases the migratory potential, the release of NETs, extracellular DNA, IL-8, ARG-1 expression, MMP9 activity, and the overall increase in viability of TNBC cells." (PMID 38398138, 2024). "ARG inhibition or myeloid cell ARG1 knock-out inhibits tumor growth in various syngeneic mouse models, which has compellingly been associated with changes of the TME immune cell composition towards a tumor-hostile environment." (PMID 39211039, 2024). "Importantly, however, and in contrast to the GLS1 enzyme, the main immunosuppressive activity exerted by ARG enzymes does not stem from their expression by tumor cells, but rather from ARG1 expressed by tumor-infiltrating immune cells." (PMID 39211039, 2024). "Mechanistically, MDSC-mediated inhibition of anti-tumour immunity occurs through a myriad of pathways including expression of arginase 1 (Arg1), inducible nitric oxide synthase (iNOS) and reactive oxygen species (ROS), and secretion of immunosuppressive cytokines such as interleukin 10 (IL-10)." (PMID 38464388, 2024). "However, we observed phenotypical changes in macrophages and other myeloid cells in Foxp3Cre-YFPIl23rfl/fl mice, marked by reduced levels of arginase-1 and CD206, which are classically linked to immunosuppression and tumor progression." (PMID 38356059, 2024). "The tumor cells of int-CAs showed coexpression of hepatocytic (HepPar1, arginase-1, or α-fetoprotein) and biliary markers (cytokeratin 19 or carcinoembryonic antigen), and at least 1 of the hepatocyte markers and 1 of the biliary markers were detected by immunohistochemical stain." (PMID 39101773, 2024). "Notably, numbers of ARG1-positive immune cells were significantly reduced by the Hes1 KO, with a decrease in the numbers of tumor-promoting TAMs that were CD163-positive macrophages." (PMID 39702544, 2024). "IL-8 silencing reduced the tumor cell capacity to induce arginase-1 release by neutrophils." (PMID 38786066, 2024). "In the inflammatory and hypoxic microenvironment of tumor-infiltrated tissues, MDSCs can secrete transforming growth factor-beta, upregulate nitric oxide, produce reactive oxygen species, and enhance the activity of arginase-1, among other mechanisms." (PMID 38885059, 2024). "Studies have shown that N1 neutrophils released molecules such as reactive oxygen species, arginase 1, and inducible nitric oxide synthase, which may regulate T‐cell immune function, promote angiogenesis, and tumor growth." (PMID 39718130, 2024). "However, the expression of molecules such as interleukin-4 (IL-4), colony-stimulating factor 1 (CSF-1) and arginnse-1 (Arg-1) in the TME are increased with the development of tumor, which induce the transformation of M1-type TAMs into M2-type TAMs." (PMID 38970071, 2024). "Meanwhile, may mainly by inhibiting the phosphorylation levels of the JAK1-STAT1 and JAK2-STAT3 pathways in tumor tissues, the expression of ARG-1, IDO, and iNOS in the TME was decreased, thus further weakening the immunosuppressive function of MDSCs." (PMID 38641823, 2024). "Enhanced activity of ARG1 in the TME may directly support tumor growth by supplying tumor cells with ornithine or ornithine-derived polyamines, which are essential for cell growth and proliferation, and by decreasing cytotoxic NO production." (PMID 39211039, 2024). "Tumor associated MDSCs highly express ARG1, depriving arginine in TME, leading to the lack of arginine in T cells and impairing T cell-mediated anti-tumor immunity." (PMID 38218942, 2024). "Furthermore, we assessed the relative mRNA levels of S100A8, S100A9, Nos2, and Arg1 in the tumor tissues." (PMID 38952044, 2024).